BRCA1 (BRCA1 DNA repair associated)
Diseases named in the same sentence as BRCA1 in open-access papers (continued):
Sharing a sentence is not in itself a finding about the gene and the disease.
tumor (continued). "Through unsupervised hierarchical clustering of each tumor by the gene-expression subtype score profiles, it was evident that a group of 4 BRCA1/2 mutated tumors, characterized by high immunoreactive subtype score, formed a unique cluster." (PMID 30382883, 2018). "The results from these BRCA1 WT PDX models also serve to model mutagenesis in the somatic tissue of patients with BRCA-deficient tumours." (PMID 30425352, 2018). "We found that tumor intrinsic molecular differences such as BRCA1/BRCA2 mutation and ER signaling were mainly associated with patient age and menopausal status." (PMID 29713003, 2018). "The medical community is encouraged to explore the activity of PARPi beyond BRCA1/2‐related malignancies toward other tumor types showing deficiency in HRR, but the currently available biomarkers to select patients have a limited positive predictive value." (PMID 30377213, 2018). "We also examined the distribution of cytoskeletal proteins in tumor tissues of BRCA1-associated lacrimal glands." (PMID 30652068, 2018). "Most importantly, only a part of the cells in both human and mouse BRCA1-deficient tumors exhibit mesenchymal features, suggesting that a subset of BRCA1-deficient tumor cells have undergone EMT." (PMID 29996906, 2018). "And, smMIPS sequencing has also recently been applied clinically to test for mutations in the tumor suppressor genes BRCA1 and BRCA2 and has demonstrated superior accuracy and turnaround time relative to previous laboratory‐developed testing." (PMID 29739035, 2018). "Because this sole case cannot establish the relationship between this germline BRCA1 mutation and tumor development as MA, the role of this famous tumor suppressor gene in MA requires further evaluation." (PMID 30111351, 2018). "Estrogen also promotes the survival of Brca1-deficient tumor cells and mammary epithelial cells (MECs)." (PMID 29996906, 2018). "Studies on mutational load, immune profile, and response to immune checkpoint inhibition in a BRCA1-deficient tumor models have provided a rationale for clinical studies of combined immune checkpoint blockade in BRCA1-associated TNBC." (PMID 30011807, 2018). "These issues limit the choice of methods suitable to robustly detect both germline and somatic BRCA1/2 variants in tumor‐derived DNA, with next‐generation sequencing (NGS) currently being the best available option to conduct full gene screening." (PMID 29215764, 2018). "Previous studies have shown that BRCA1-deficient OC are more likely to display high levels of tumour infiltrating lymphocytes (TILs) and display an enrichment of immune response genes." (PMID 29298688, 2018). "Estrogen stimulated the proliferation and tumor-initiating potential of both ER-positive Brca1-proficient and ER-negative Brca1-deficient tumor cells." (PMID 29996906, 2018). "Multiple studies have demonstrated the tumor-promoting interplays between RSF-1 and known oncogenes or tumor suppressors, such as cyclin D1, cyclin E1, retinoblastoma (RB) and breast cancer susceptibility gene 1 (BRCA1)." (PMID 29480799, 2018). "Mutation signature associated with DNA mismatch repair deficiency and high mutation frequency (Signatures 20, 6, and 14) was only evident in the high mutation burden tumor with both BRCA1 and MLH1 inactivation." (PMID 30382883, 2018). "Collectively, these findings suggest that impaired H2A ubiquitination-mediated satellite DNA suppression is associated of BRCA1-related defects, providing a potential new function of BRCA1 in tumor suppression." (PMID 30558184, 2018). "BRD4-amplified HGSOC tumors are mutually exclusive with BRCA1/2 mutations and therefore represent a tumor subtype with few therapeutic options beyond platinum-based chemotherapy." (PMID 30036377, 2018). "Overall, these results have encouraged the medical community to explore the activity of PARPi beyond BRCA1/2‐related malignancies toward other tumor types showing deficiency in HRR." (PMID 30377213, 2018).
tumor (continued). "For example, DNA hypermethylation of promoter regions can cause transcriptional silencing of tumor-suppressor genes; BRCA1 hypermethylation has been shown to alter responses to platinum-salt therapies." (PMID 29322935, 2017). "Both of these therapeutics are thought to best target tumor cells with deficiencies in HR DNA repair, such as those with BRCA1/2 mutations." (PMID 28649435, 2017). "Our novel method enables reliable assessment of the tumor DNA mutation status of BRCA1 and BRCA2 in FFPE material derived from OCs." (PMID 27767231, 2017). "Durable responses to PARP inhibitors have been associated with the inactivation of both BRCA1/2 alleles in the tumor; in this case, emergence of one putatively functional allele was detected at progression." (PMID 29262651, 2017). "On the other hand, low socio-economic status, young age at diagnosis, and BRCA1 mutation are more strongly associated with HR-negative tumours, and somewhat closer to SSA reality." (PMID 28900476, 2017). "The 55% rate of BRCA1/2 mutations in the Study 19 tumor-sequenced subpopulation was higher than the 20-26% rate seen in other HG-SOC tumor-sequencing studies." (PMID 28525389, 2017). "Breast cancer susceptibility gene 1 (BRCA1) is a tumor suppressor gene, and its protein BRCA1 plays a role in DNA repair." (PMID 28359295, 2017). "It is to be noted that its superior potency when compared with BRCA1/2 wild-type and mutated cells is an advantage in tumours that express BRCA1/2 heterogeneously." (PMID 28800752, 2017). "Tumors arising from BRCA1 mutation carriers usually show loss of the wild-type (wt) allele, which renders tumor cells biallelically null for the gene." (PMID 28398198, 2017). "To verify this, we compared tumours with known BRCA1/2 deficiency and wild-type tumours using 319 tumours with level 3 mutation data of the TCGA dataset." (PMID 29116111, 2017). "This further explains tumor growth inhibition by acetaldehyde in BRCA1/2‐deficient tumors, including those that have acquired resistance to PARP inhibitors." (PMID 28729482, 2017). "In our study, the high risk of ER-/PR- CBC following a first tumor with the same phenotype persisted after we excluded BRCA1/2 mutation carriers." (PMID 28724391, 2017). "Associations of BRCA1 expression with patient, clinical and tumor characteristics were broadly similar between compartments (nuclear or cytoplasmic)." (PMID 28863181, 2017). "The analysis of DMD genetic alterations revealed a high frequency of gene mutations, which was similar to other well-known tumor suppressor genes (BRCA1, BRCA2, PTEN, RB1)." (PMID 27391342, 2017). "Spontaneous base substitution mutation rates increased sevenfold upon the disruption of either BRCA1 or BRCA2, and the arising mutation spectra showed strong and specific correlation with a mutation signature associated with BRCA1/2 mutant tumours." (PMID 27452521, 2017). "It is generally believed that genome instability resulting from the DNA repair defect following the loss of BRCA1 is a driver of tumor development." (PMID 28398198, 2017). "PARP inhibitors proficiently result in synthetic lethality in tumor cells with BRCA1/2 or other HRR deficiencies, more than in normal DNA repair proficient cells." (PMID 29050241, 2017). "Patients with Nestin protein expression in tumour cells more often had BRCA1 germline mutations (OR 8.7, p < 0.0005, Series III), especially among younger patients (<40 years at diagnosis) (OR 16.5, p = 0.003)." (PMID 28439082, 2017). "Germline DNA specimens were available for 28 of the patients harboring a BRCA1 or BRCA2 tumor mutation." (PMID 28250960, 2017). "We herein provide the first description of the BRCAness phenotype of the HCC70 TNBC cell line and report that the BRCAness profile shares common metabolic features with BRCA1-mutated tumours." (PMID 29259228, 2017). "Frequent losses in 4q and 5q in BRCA1-mutated tumours have distinguished them from sporadic neoplasms." (PMID 28351365, 2017).
tumor (continued). "By analyzing our set of tumor samples, we found an association between the BRCA1 promoter methylation status and the hormone receptor status." (PMID 28403857, 2017). "Because of results in preclinical models, BRCA1 mutation carriers of multiple tumor types have been enrolled in clinical trials with PARP inhibitors." (PMID 28851423, 2017). "PAR pathway is particularly interesting because of the promising drugs act on inhibiting PAR polymerizing enzyme (PARP) are more efficient in cells BRCA1 mutated with saved BARD1 tumor suppressor function." (PMID 29292755, 2017). "Reduced nuclear expression of BRCA1 was associated with higher tumor grades; grade 2 and 3 (60%) versus 42% in grade 1 (χ2 = 4.6, p b = 0.035)." (PMID 28863181, 2017). "Lower BRCA1 N/C ratio was associated with early family history, basal-like nature of the tumor, and a high proliferation index (Ki67)." (PMID 28863181, 2017). "The present study analyzes the Study 19 BRCA1/2 mutational data from a tumor-based perspective, focusing on the 209 patients with tumors successfully sequenced by NGS." (PMID 28525389, 2017). "The tumor cells with BRCA1/2 mutation or other HRR defective status cannot efficiently repair these double-strand breaks, leading to cell death." (PMID 29050241, 2017). "This novel tumor suppressor is intriguing because of not only its known association with BRCA1 but also its established functions in the regulation of cell cycle, cell growth, and cell proliferation, among other key cellular functions." (PMID 29088836, 2017). "The observation that HELB-depleted BRCA1-deficient tumor cells were resistant to a PARP inhibitor is consistent with an auto-regulatory mechanism to limit end-resection dependent on HELB and its interaction with RPA." (PMID 28594346, 2017). "Ten out of 14 unstable tumours fell within the top quintile of the BRCA signature which was associated with deleterious mutations of BRCA1 (n = 2), BRCA2 (n = 7), and PALB2 (n = 2)." (PMID 29069866, 2017). "Three different patient tumours were compared initially: two containing deleterious BRCA1 or BRCA2 mutations and one wild type status." (PMID 28211448, 2017). "Consistently, in the BRCA1-deficient MDA-MB-436 xenograft tumor cells, the levels of γH2AX, a DSB marker, increased in time- and dose-dependent manners." (PMID 27926532, 2017). "Future studies will shed light on the underlying mechanism by which BRCA1/COBRA1-regulated R-loop dynamics influences BRCA1-associated tumour development." (PMID 28649985, 2017). "HRDetect identifies BRCA1/BRCA2-deficient tumours with 98.7% sensitivity (area under the curve: 0.98)." (PMID 28491135, 2017). "In this study of platinum-sensitive, relapsed HG-SOC, NGS was performed on hybridization-capture-enriched, formalin-fixed paraffin-embedded (FFPE)-derived tumor genomic DNA and accurately identified BRCA1/2 mutations." (PMID 28525389, 2017). "This tumor was BRCA1 mutated, and had an observed increase in expression in AKT3 and PIK3CA, and a significant decrease in expression of PTEN, demonstrating an active PI3K/AKT pathway." (PMID 28649657, 2017). "Other evidence suggests that aberrations on the X chromosome are common to both BRCA1-mutated and sporadic tumours." (PMID 28351365, 2017). "Most tumours associated with germline BRCA1/BRCA2 loss of function mutations respond to DNA damaging agents, however, some do not." (PMID 28831036, 2017). "Tumours that arise in patients carrying BRCA1 germline mutations tend to be triple negative breast cancers (TNBC)." (PMID 29259228, 2017). "In this case, the BRCA1 mutation was found only in the tumor, thus confirming that this mutation was of somatic origin." (PMID 28497333, 2017). "Among the normal-like tumor forming cell lines, the BRCA1-mutated MDA-MB-436 harbored more CD44+/24–/low cells (95 ± 1.4 %) than MDA-MB-231 (90.67 ± 1.75 %)." (PMID 27229859, 2016).
tumor (continued). "Increased tumor-derived DNA methylation was identified across all 15 BRCA1 promoter-associated probes with an average Δβ of 11.24% (adj." (PMID 27902704, 2016). "Nevertheless, it remains enigmatic why a mutation in a single copy of BRCA1 leads to rapid tumor onset in a very strict tissue- and cell-type-specific manner." (PMID 27259235, 2016). "The currently known BRCAness tests (aCGH and the 60-gene expression based) were both developed based on the detection of patterns in sporadic tumors that are signatures of BRCA1 mutated tumor." (PMID 27077368, 2016). "The Brown and Palmer study was based on occult tumor size data collected from healthy germline BRCA1 mutation carriers who had their ovaries and Fallopian tubes prophylactically removed." (PMID 27257824, 2016). "This is consistent with a previous study showing that 53BP1 loss confers PARP inhibitor resistance in BRCA1-deficient tumor cells." (PMID 27613518, 2016). "This includes BRCA1/2 mutation carriers, whose sole option for actively reducing tumor burden currently involves risk-reducing surgery (mastectomy, adnexectomy)." (PMID 27590516, 2016). "Database review from two institutions identified 46 tumor samples from patients with germline BRCA1 mutations and 35 tumor samples from patients with germline BRCA2 mutations from 1995 to 2013 with available tissue for immunohistochemistry (IHC) staining." (PMID 27708239, 2016). "Our analyses reveal that germline mutations F1662S and M1663K disrupt the ability of BRCT to dimerize, in vitro and in vivo, providing a structural explanation for the possible role of these mutations in inactivating BRCA1 tumor suppressor function." (PMID 26778126, 2016). "Germline BRCA1 P/LP variants, which were associated with aggressive tumor phenotypes, predicted worse disease-free survival in the subgroup of stage 0~II (HR: 4.52, P = 0.02) and N0 (HR: 5.4, P = 0.04) compared to non-carriers." (PMID 27257965, 2016). "There is accumulating evidence that BRCA1 haploinsufficiency is a driver of tumor predisposing events in BRCA1 mutation carriers." (PMID 27534398, 2016). "BRCA1 is a tumor suppressor, and its function has been linked with multiple pathways including DNA damage repair and oxidative stress regulation." (PMID 27811360, 2016). "Tumor cells carrying the mutations of the tumor suppressor genes BRCA1 or BRCA2 are defective in homologous recombination, and thus are sensitive to the inhibition of PARP activity, another key pathway involved in DNA repair." (PMID 26933818, 2016). "BRCA2 or IHC features, and therefore concurrent review of BRCA1/2 mutational screening together with tumor markers have rarely been reported." (PMID 27478808, 2016). "Given the function of Brca1 in DNA damage repair, we also evaluated the role of Brca1 loss in inducing DNA damage in tumor development." (PMID 27811360, 2016). "We have also shown for the first time that TBXA2R is transcriptionally repressed by BRCA1 (a tumour suppressor often mutated or down-regulated in TNBC), providing a potential mechanism by which TBXA2R is up-regulated in TNBC/BLBCs." (PMID 27487152, 2016). "Our finding showed that BRCA1 knockdown induced the expansion of the CD49f+EpCAM+ subpopulation in the CD44+CD24– cell subset of MCF10DCIS tumor cells, confirming the relationship between BRCA1 deficiency and luminal progenitors." (PMID 27556296, 2016). "For example, the level of genomic instability of mouse tumors carrying the BRCA1-C61G RING inactivating mutation is identical to that of BRCA1-null tumors, tumor cells with BRCA1-C61G RING inactivating mutation develop a resistance to PARP-inhibition." (PMID 27634150, 2016).
tumor (continued). "Mutations in this region affect BRCA1′s ability to repair DNA and also hinder its ability as a tumor suppressor." (PMID 30460281, 2016). "This indicates tumor suppression according to Knudson ́s two hit model, analogous to that of BRCA1/BRCA2 mutation carrier tumors." (PMID 26820313, 2016). "A number of epidemiologic reports suggest tumor type predisposition differs according to the position of the BRCA1 mutation." (PMID 27534398, 2016). "This sensitivity is exploited in the clinic through selective targeting of BRCA1/2‐deficient tumours with ICL‐inducing agents, including MMC and cisplatin." (PMID 27037238, 2016). "Univariate and multiple logistic regression models were used to investigate possible differences in prevalence of BRCA1/2 mutations according to patient and tumor characteristics." (PMID 27553291, 2016). "The clinical consequences of a confirmed BRCA1 or BRCA2 mutation include intensive screening for early tumour detection." (PMID 27881737, 2016). "During the variant calling process, we identified pathogenic mutations in four of the ten tumor samples, all of them present in BRCA1: a frame-shift insertion (c.5263_5264insC) and two nonsense mutation (c.628C>T and c.5251C>T)." (PMID 27533253, 2016). "Patients with a BRCA1 deficiency develop BLBCs that are enriched with tumor-initiating cells (TICs) and exhibit epithelial-mesenchymal transition (EMT) characteristics." (PMID 27811360, 2016). "Triple negative tumours in young women with multiple BRCA1-like morphological features are associated with hypermethylation of the BRCA1 promoter in blood DNA." (PMID 27463681, 2016). "Although somatic mutations in BRCA1 gene represent about 40 %, there is a highly dysfunction in BRCA1 within tumor cells by other mechanisms, notably epigenetic modifications like gene methylation." (PMID 27770782, 2016). "Many tumor-derived truncation and missense mutations have been identified in the BRCA1 BRCT domains." (PMID 26778126, 2016). "BRCA1 is a tumor suppressor found to be mutated in hereditary breast and ovarian cancer and plays key roles in the maintenance of genomic stability by homologous recombination repair." (PMID 28009280, 2016). "BRCA1/2 mutations were identified using next-generation sequencing of formalin-fixed paraffin-embedded tumor samples." (PMID 27907908, 2016). "Although originally developed as chemosensitisers, these compounds induce synthetic lethality in tumour cells from patients carrying germline loss-of-function mutations in DNA damage pathway tumour suppressor genes BRCA1 and BRCA2." (PMID 27702751, 2016). "Tumours arising in women with hereditary BRCA1 mutations tend to be TN and basal-like, features that are associated with a poor prognosis." (PMID 27463681, 2016). "The tumor suppressor genes BRCA1 and BRCA2, which were both up-regulated in bats, encode proteins that are pivotal in maintaining genomic stability by promoting efficient and accurate repair of DNA double-strand breaks." (PMID 27832764, 2016). "It has been reported that inhibition of RAD52 either by specific shRNA or a small peptide aptamer induced synthetic lethality in tumor cell lines carrying BRCA1 and BRCA2 inactivating mutations." (PMID 26784987, 2016). "One-third (4/12) of the deleterious BRCA1/2 mutations occurred in tumor tissues only (somatic mutations)." (PMID 27907908, 2016). "Our results are consistent with a smaller study that found that 21% of 30 BRCA1-associated ER-negative breast cancers expressed the AR using the same criteria of at least 1% of tumor nuclei staining." (PMID 28721372, 2016). "The prevalence of BRCA1 mutations also varied with tumor grade; women affected by grade 3 tumors showed the highest risk of carrying a BRCA1 mutation (Global P < 0.0001)." (PMID 27553291, 2016). "We then computed a composite BRCA1 Deficiency Score (BDS) by adding the individual scores for the three variables for each tumor." (PMID 27077368, 2016).